IDO1 (indoleamine 2,3-dioxygenase 1)
Diseases named in the same sentence as IDO1 in open-access papers (continued):
Sharing a sentence is not in itself a finding about the gene and the disease.
tumor (continued). "In fact, research has proven that blockage of IDO1 activity can directly enhance the immune capacity of tumor-bearing mice against the tumors." (PMID 29468141, 2018). "Tumor cells evade immunosurveillance through various mechanisms, including checkpoint inhibition of T cell activation and upregulation of IDO1 that catalyzes tryptophan degradation in the kynurenine pathway." (PMID 29685162, 2018). "At this stage, IDO1 is produced at low levels within the tumor microenvironment and inhibits tumor proliferation." (PMID 29445380, 2018). "There was a substantial increase of IDO1 expression in immune cells at the tumor microenvironment over time." (PMID 30186285, 2018). "IDO1-mediated suppression through mTORC1 triggers autophagy, leading to anergy in T cells in the tumor microenvironment." (PMID 30068361, 2018). "Treg cells are a major suppressive cell type in the tumor microenvironment, as their recruitment is induced by high IDO1 levels and correlates with poor prognosis in several tumor types." (PMID 30068361, 2018). "In contrast, non-malignant tissue counterparts of these five cancer types do not show any statistically significant correlations and express less IDO1 compared to their tumour tissue counterparts." (PMID 30466445, 2018). "Preliminary in vivo experiments suggest that treatment of tumor-bearing mice with mIDO1-specific ASOs results in the knockdown of IDO1 in tumor cells as well as tumor infiltrating myeloid cells." (PMID 30400822, 2018). "IDO1’s role in neovascular development suggests that when clinical results of IDO1 inhibitors are assessed, the impact on tumor vasculature should be examined." (PMID 30068361, 2018). "Mesenchymal stem/stromal cells in the tumor microenvironment promote tumor growth through IDO1-mediated immune suppression." (PMID 30068361, 2018). "In the “escape” phase, IDO1 is produced in large quantities by tumor cells and tolerogenic immune cells that are recruited to the tumor microenvironment." (PMID 29445380, 2018). "Obviously, compound 20a significantly inhibited IDO1 activity in tumor tissues and reduced Kyn level in plasma with IDO1 inhibitory IC50 value of 0.13 μM and antiproliferative EC50 (half maximal effect concentration) value of 0.27 μM aganist HeLa cells." (PMID 30618747, 2018). "Originally, IDO1 has been considered as an anti-cancer molecule, proposing that increased IDO1 activity of antigen-presenting cells depletes the essential amino acid Trp from tumor cells and inhibits their growth." (PMID 29445380, 2018). "IDO-1 expression levels in tumor endothelial cells were further suggested being a predictive biomarker for the response to immune-based cancer therapy." (PMID 30250827, 2018). "Previous work has demonstrated that interferon-gamma (IFNɣ) secreted in the tumor microenvironment increases IDO1 expression, similar to PD-L1." (PMID 29805749, 2018). "IDO1 (indoleamine 2,3-dioxygenase 1) is a tryptophan-catabolizing enzyme that fosters a tumor-promoting inflammatory microenvironment." (PMID 30400835, 2018). "In this review, we discuss the function of the IDO1 pathway in tumor progression and immune surveillance." (PMID 30068361, 2018). "Inhibitors targeting the indoleamine-2,3-dioxygenase 1 enzyme (IDO1) represent one of the most potent therapeutic opportunities to inhibit tumor growth." (PMID 29445380, 2018). "The tryptophan catabolic enzyme indoleamine 2,3-dioxygenase-1 (IDO1) has received a great deal of attention as a driver of tumor-mediated suppression." (PMID 30254983, 2018). "Blockade of IDO1 activity decreased tumor proliferation in a T-lymphocyte-mediated manner and enhanced the efficacy of chemotherapy, radiotherapy, targeted therapy, and immunotherapy." (PMID 30068361, 2018). "In animal studies, genetic inhibition of IDO1 expression reactivated the antitumor immune response against IDO+ cancer cells and inhibited tumor growth." (PMID 29445380, 2018).
tumor (continued). "More precisely in various types of cancer, IDO1 expression has been confirmed, individually or in combination, in tumor cells, in interstitial cells in lymphocyte-rich areas, and in endothelial cells." (PMID 30150994, 2018). "Potent mouse specific IDO1 ASOs have been identified and will be used for in vivo efficacy studies in tumor-bearing mice." (PMID 30400822, 2018). "A phase I trial of tumour patients using 1-MT (D-isomer) as an IDO1 inhibitor has shown that doses higher than 1200 mg 1-MT/patient do not increase peak serum levels, indicating a limited accumulation of the applied 1-MT." (PMID 30279361, 2018). "The overexpression of IDO1 in tumor cells, as well as in the dendritic cells (DCs) that localise to the tumor draining lymph nodes, has been shown to be correlated with reduced overall survival in patients." (PMID 29932010, 2018). "We furthermore developed ASOs with specificity for murine IDO1 (mIDO1) to investigate the efficacy of ASO-mediated IDO1 knockdown in syngeneic tumor models." (PMID 30400822, 2018). "To mimic the effect of IDO1 on T cell activation in a tumor microenvironment we utilized a co-culture of IDO1 expressing SKOV-3 cells with Jurkat T cells." (PMID 30112109, 2018). "IFNγ induces the expression of some tolerant molecules, such as CTLA‐4, PD‐L1 and indolamine‐2,3‐ dioxygenase‐1 (IDO1) on/in tumor cells." (PMID 30039553, 2018). "For the sensitive detection of Trp metabolites in IDO1+ tumor tissues, a wealth of Trp-based radiotracers has been developed for positron emission tomography imaging." (PMID 29445380, 2018). "By inhibiting IDO1 and decreasing Kyn levels in tumor cells, BMS-986205 reversed immunosuppression in cancer patients." (PMID 30068361, 2018). "When administrated to the B16F10 tumor-bearing mice, Roxyl-WL can inhibit IDO1 activity, suppress the tumor growth, reduce the number of Foxp3+ Tregs, and decrease the Kyn/Trp ratio evidently." (PMID 29932010, 2018). "On the other hand, IDO1 is a crucial innate immunity regulator that acts by depleting Trp in both the inflammatory and tumor microenvironments." (PMID 30068361, 2018). "IDO-1 expression can be found in different tumor cells, normal epithelial cells, monocyte-derived cells and in particular also in tumor endothelial cells." (PMID 30250827, 2018). "Concerning the challenge to overcome the tumor-mediated immunosuppression, melatonin showed inhibitory effects on the immunomodulatory enzyme indoleamine 2,3-dioxygenase-1 (IDO1)." (PMID 30186285, 2018). "The increased frequencies of IDO1-expressing cells, such as DCs, macrophages, inflammatory monocytes and MDSC, in mice transplanted with TC-1 cells indicated that the use of IDO1 inhibitors would improve tumor growth control." (PMID 30186285, 2018). "One of these factors, indoleamine 2,3-dioxygenase 1 (IDO1), is overexpressed in a number of human malignancies in both tumor and stromal tissue, and is a major contributor to cancer-induced immune evasion." (PMID 29805749, 2018). "In cancer cells, IDO1 mediates an acquired immunosuppression leading to local and systemic immune tolerance towards the tumor by helping to evade immune surveillance." (PMID 29921320, 2018). "As per our previous report the IFNg potentially from T cell activation or other sources induces PD-L1 and IDO1 and potentially contribute to aggressive disease and worse outcomes in basal subtype tumours." (PMID 30308033, 2018). "In this scenario, the combination of IDO1 inhibitors with immunotherapies and other anti-cancer drugs seems to be particularly encouraging and emphasizes the relevant role of tumor biology knowledge in the development of more efficient therapies." (PMID 30186285, 2018). "Initial findings that IDO1 peptide-derived vaccines can elicit effective anti-tumor responses demonstrate the utility of mouse models for further exploration and refinement of this novel approach to IDO1-directed cancer therapy." (PMID 30400835, 2018).
tumor (continued). "These adverse effects of 1-MT should be considered in therapeutic applications of 1-MT, which is used in clinical studies in tumour patients with the goal of preventing IDO1-induced immune escape of cancer cells." (PMID 30279361, 2018). "Usually IDO expression in murine tumor cells is observed after transfection of cells with IDO1 encoding viruses or after genetic manipulations." (PMID 30186285, 2018). "IDO1, the most active isoform, is expressed in diverse tumor types and can be targeted using small molecule inhibitors." (PMID 29037255, 2017). "Associations between IDO1, clinico-pathological features and CD3+, CD8+, CD20+ and FOXP3 tumor-infiltrating lymphocytes were examined using χ2 and Mann-Whitney tests." (PMID 29037255, 2017). "The frequencies of tumor-associated immunosuppressive factors, including the COX2, IL-10, NOS2 and IDO1 mRNA was abrogated by the addition of COX2 inhibitor during the generation of CM from cancer ascites cells." (PMID 29163789, 2017). "IDO1 negatively regulates T cells in the tumor microenvironment by catabolizing tryptophan, thereby inducing an amino acid starvation response to which T cells are highly sensitive." (PMID 28546465, 2017). "These experiments provide initial evidence that IDC cells, in part via IFNγ, induce endogenous IDO1 expression by ECs serves as an evasive mechanism against TSP1 of tumour dormancy." (PMID 29156701, 2017). "Meanwhile, Salmonella reduced the expression of IDO-1 in tumors, which increased infiltrating immune cells such as macrophages, neutrophils and T cells, within the tumor sites." (PMID 28456782, 2017). "Recent studies suggest that IDO1 plays a crucial role in the induction of immune tolerance to tumours." (PMID 28465467, 2017). "Indoleamine 2,3 dioxygenase (IDO-1), an enzyme in the kynurenine pathway, plays a critical role in tumor-mediated immune tolerance." (PMID 29038460, 2017). "Alternatively, the mechanism of anti-T cell immunity of IDO1 can also be attributed to plasmocytoid dendritic cell expression of IDO1 in tumor-draining lymph nodes." (PMID 28191010, 2017). "Several human cell types have been detected to express IDO1, such as activated dendritic cells, macrophages, endothelial cells, fibroblasts and multiple tumour cells." (PMID 29156701, 2017). "Kunle Odunsi, MD, PhD (Roswell Park Cancer Institute Center for Immunotherapy) presented a study (NCT02042430) designed to investigate the effects of indoleamine 2, 3-dioxygenase (IDO)-1 inhibition via oral INCB024360 on the tumor microenvironment (TME)." (PMID 28716068, 2017). "IDO1 controls an immune surveillance pathway in the tumor microenvironment (TME) by catalyzing a rate-limiting step in the kynurenine pathway." (PMID 29180759, 2017). "In tumour-bearing mice, fludarabine also effectively decreased IDO1 in HCC induced by MV-Edm and adoptive CD8+NKG2D+ cells, leading to an enhanced antitumour immune responses and prolonged survival." (PMID 28701757, 2017). "TSP1 levels in the tumour stroma were negatively correlated with vascular indoleamine 2,3-dioxygenase 1 (IDO1) in IDC tissues." (PMID 29156701, 2017). "Indoleamine 2,3 dioxygenase-1 (IDO-1) is an enzyme in the kynurenine pathway which augments tumor-induced immune tolerance." (PMID 29038460, 2017). "There was a positive correlation between IDO1 scores in the stromal compartment and tumor cells (R2 = 0.56)." (PMID 29037255, 2017). "Overexpression of IDO1 has been observed in various cancer cells and antigen-presenting cells, and depletion of IDO1 has been shown to inhibit tumor growth and metastases." (PMID 29120388, 2017). "After all, if IDO1 is derived from the tumor, the expression of IDO1 in cultured cells cannot be lower than that of the autologous non-affected lung tissues." (PMID 28903363, 2017). "This study investigated the distribution of radiofluorinated carboximidamides as novel imaging tools in tumor-bearing animals with the aim to determine specific accumulation in IDO1 expressing tumors." (PMID 28159919, 2017).
tumor (continued). "In fact, tumor-immune interactions are complex and also involve a significant number of soluble factor inhibitors, such as kyneuranines, which are produced by IDO1." (PMID 28159919, 2017). "The authors proposed that IDO1 influenced tumor development by regulating epithelial cell proliferation via β-catenin." (PMID 28191010, 2017). "The PRAD N-model (mean AUC = 0.986) includes an isoform of IDO1, a gene related to anti-tumor defense." (PMID 27535130, 2016). "It has previously been shown in the P815 murine tumor model that potentially immunogenic tumor cells that express IDO1 are protected from immune-mediated rejection, and that treatment with the IDO-inhibitor 1-MT can revert this effect." (PMID 27192116, 2016). "Indoleamine 2, 3-Dioxygenase 1 (IDO1) in cancer cells plays a critical role in tumor immunosuppression." (PMID 26895379, 2016). "In MB cell lines, inhibition of mTOR strongly induced IDO1 expression and activity, corroborating its ability to recruit Treg cells in the tumor microenvironment." (PMID 27174915, 2016). "The IDO1 inhibitor epacadostat can interact with NK cells as well as CTLs and IDO1-producing tumor cells in regulating the immune responses." (PMID 27192116, 2016). "Mechanistically, immune cells were required for the induction and maintenance of IDO1 expression in human tumor cells." (PMID 26895379, 2016). "Extending the current knowledge on cancer-related inflammation, our present study suggested an adaptive tumor immune escape mechanism, which is overexpression of immunosuppressive IDO1 under the stimuli of IFN-γ derived from immune cells." (PMID 26895379, 2016). "Antisense-mediated reduction of IDO1 expression reduced intracellular NAD+ in A549 human tumor cell line by approximately 60%." (PMID 27058624, 2016). "Tumoral IDO1 expression plays an indispensable role in local immune suppression within the tumor microenvironment." (PMID 26895379, 2016). "Taken together, these observations supported that the induction and maintenance of IDO1 in tumor cells are regulated by tumor-infiltrating inflammatory cells." (PMID 26895379, 2016). "Over the past decade strong evidence has accumulated that confirms that IDO1/TDO2 overexpression in tumour results in tryptophan depletion in the microenvironment, in turn, suppressing the T-cell mediated immune response." (PMID 26646699, 2016). "As the in vitro data suggested that monocytes and T lymphocytes cooperated to induce IDO1 expression in tumor cells, we further confirm our finding in vivo." (PMID 26895379, 2016). "IDO1 has been recognized as an important mediator for tumor immune suppression, but it precise regulating mechanisms in human cancer cells are not fully understood." (PMID 26895379, 2016). "In the tumor tissue, expression of IDO1 was greater than its isoform IDO2, suggesting a regulatory role for IDO1 in mediating immunosuppression and inducing downstream GCN2 expression." (PMID 27705910, 2016). "A particularly interesting recent development has been the discovery of the role of IDO1 in mediating tumour immune-evasion." (PMID 26646699, 2016). "This potentially highlights the different roles (pro- and anti-tumorigenic) of elevated IDO1 expression within tumour cells as well as its microenvironment." (PMID 26646699, 2016). "IDO1 activity also directly promotes tumor growth and proliferation of the neoplastic epithelium in a cell-autonomous fashion via the generation of Kyn metabolites and activation of beta-catenin signaling." (PMID 27578919, 2016). "Strikingly, all tumor cells showed significant IDO1 expression by western blot after a 2-day co-culture with PBMC, at levels comparable to those induced by IFN-γ." (PMID 26895379, 2016). "The intracellular distribution of IDO1 protein within tumor cells was confirmed by immunocytochemistry." (PMID 26895379, 2016). "Mechanistically, we showed that IDO1 expression in tumor cells was only induced when co-cultured with both T lymphocytes and monocytes." (PMID 26895379, 2016).
tumor (continued). "Further studies are warrant to investigate clinical benefit of cancer immunotherapy targeting IDO1 in tumor patients." (PMID 26895379, 2016). "Among 30 tumoral IDO1+ positive samples, 22 (73%) contained less than 10% IDO1-positive tumor cells, 8 (26%) contained 10-50% IDO1-positive tumor cells, while few with more than 50% positive." (PMID 26895379, 2016). "IDO1-positive cancer cells were detected in nearly half of the tumor samples analyzed (47%, 30 of 64)." (PMID 26895379, 2016). "We grouped the tumors into 3 categories according to the proportion of tumor cells positive for IDO1." (PMID 26895379, 2016). "More importantly, strong IDO1 expression in tumor cells was observed in the xenograft of co-implantation group." (PMID 26895379, 2016). "Since all host tissues and tumor-infiltrating immune cells lack Ido1 in IDO−/− mice, these data suggest that only the transplanted LLC tumor cells contribute to IDO expression in the IDO−/− mice." (PMID 27705910, 2016). "Our present study showed constitutive expression of IDO1 in tumor cells of various cancer types is rare, and cooperation of T cells and monocytes induce tumoral IDO1 expression through inflammatory cytokine." (PMID 26895379, 2016). "Collectively, our data indicated that cooperation of T lymphocytes and monocytes are indispensable for the up-regulation of IDO1 in tumor cells in vitro." (PMID 26895379, 2016). "Collectively, our data revealed that T lymphocytes and monocytes play an indispensible role on IDO1 induction in tumor cells in vivo." (PMID 26895379, 2016). "In contrast, tumoral IDO1 expression was induced when tumor cells were cocultured with PBMC or a mixture of monocytes and T cells." (PMID 26895379, 2016). "These cells are capable of lysing tumor cells and DCs expressing IDO1, which boosts the immune response." (PMID 27192116, 2016). "Previous work has shown that inhibition of IDO-1 restores activity of T cells in the tumor environment, but the potential of IDO inhibition to alter the overall tumor immune landscape has not been determined." (PMID 27572319, 2016). "Since IDO1 inhibitors are now being developed clinically for the treatment of several cancers with the aim of reversing cancer-associated immune suppression, we speculate that a possible targeting of IDO1 in MB could improve tumor eradication by acting at different levels." (PMID 27174915, 2016). "IDO1, which has been extensively characterized as an inhibitor of immune responses in the tumor microenvironment, was observed to be upregulated in all the three non-self tissues." (PMID 27852037, 2016). "Despite the expression and immune-suppressive role of IDO1 have been well documented in numerous studies, one unclear question is how IDO1 in human tumor cells is regulated by tumor milieus." (PMID 26895379, 2016). "Studies utilizing murine cancer models confirmed that IDO1/TDO2 over-expressing tumours are more aggressive compared to tumours with basal IDO1/TDO2 levels." (PMID 26646699, 2016). "A recent study reported by the Koropatnick group shows that IDO1, expressed in tumor cells, presents immune-independent function in response to chemotherapeutic and radioactive drugs." (PMID 27058624, 2016). "Here, we reported that IDO1 expression in tumor cells of hepatocelluar carcinomas (HCC), displayed a discrete rather than uniform pattern." (PMID 26895379, 2016). "Intriguingly, rapamycin was able to induce IDO1 expression, contributing to tumor immune escape mechanism." (PMID 27174915, 2016). "It has been reported that IDO1 impedes tumor cell proliferation and IDO1-mediated depletion of tryptophan induces cell cycle arrest in T cells at G1." (PMID 27058624, 2016). "Similar to CTLA-4, up-regulation of IDO1 or TDO2 allows tumor cells to evade antitumor immunity check from host T cells." (PMID 28027300, 2016). "In particular, IDO1 induces expansion of regulatory T-cells (Treg), preventing immune response against tumor cells." (PMID 27174915, 2016).